ENSG00000223027
Synonyms: LOC124900293
Gene: Small nucleolar RNA gene on chromosome 10 (26,789,017 to 26,789,157, forward strand). Ensembl gene ENSG00000223027.
Gene Ontology:
Biological process: RNA processing
Cellular component: nucleolus
Homologues: Paralogues in human: SNORA57 (80% identical).